INS (insulin)
Diseases named in the same sentence as INS in open-access papers (continued):
Sharing a sentence is not in itself a finding about the gene and the disease.
liver cirrhosis (continued). "Therefore, we conducted this retrospective cohort study to investigate the long-term outcomes of insulin use in people with T2DM and compensated liver cirrhosis." (PMID 34118892, 2021). "The exact mechanisms through which liver cirrhosis can lead to DM are not well defined, but there is growing evidence that both insulin resistance and β-cell dysfunction contribute." (PMID 33409325, 2020). "Progressively increasing adiponectin levels elicited a positive impact on glucose homeostasis, but not insulin sensitivity across liver cirrhosis stages." (PMID 32092909, 2020). "Given their fragility and frequent admission, it is recommended to treat patients with decompensated liver cirrhosis with basal long-acting insulin analogs with or without rapid-acting insulin analogs, carefully titrating the insulin doses and closely monitoring the blood glucose levels." (PMID 35252271, 2022). "It was also found that therapies with BCAAs did not raise the concentrations of glucose in patients with liver cirrhosis and prolonged essential amino acid supplementation (with 62% BCAAs) did not decrease insulin sensitivity in healthy older adults with moderate protein intake." (PMID 34684308, 2021). "Notably, when administering SGLT2is to patients with low insulin secretion who are not administering extrinsic insulin, serum ketone concentrations may increase or ketoacidosis may occur, and this is particularly true when administering these drugs to patients with liver cirrhosis." (PMID 33457424, 2020). "Similar significant joint effects of ALT > 40 U/L with NAFLD, liver cirrhosis, HBV and HCV infection, and any one of these CLDs were observed in insulin, and non-insulin users." (PMID 29262605, 2017).
neonatal diabetes mellitus (46 papers, 2007 to 2026). Neonatal diabetes mellitus presents as hyperglycemia, failure to thrive and, in some cases, dehydration and ketoacidosis which may be severe with coma, in a child within the first months of life. "We analyzed a novel insulin gene (INS) mutation of a Chinese permanent neonatal diabetes mellitus (PNDM) patient to explore the clinical and genetic characteristics and put forward some opinions on treatment and its long-term management." (PMID 36686471, 2022). "Channel hyperactivation is associated with reduced insulin secretion and neonatal diabetes mellitus, whereas reduced channel activity leads to enhanced insulin secretion and congenital hyperinsulinism." (PMID 36047384, 2022). "Upon exome sequencing, he was found to be heterozygous for a de novo missense mutation in the insulin gene (INS) which is associated with permanent neonatal diabetes mellitus or type 1b diabetes mellitus." (PMID 26284228, 2015). "This is supported by studies of the Akita mouse and in some patients with neonatal diabetes mellitus (NDM) that arise from mutations in the Insulin gene, resulting in improper folding of the mutant protein." (PMID 25144761, 2014). "Mutations in the insulin (INS) gene may result in permanent neonatal diabetes mellitus (PNDM) in humans." (PMID 32575461, 2020). "The patient had a history of recurrent fracture, neonatal diabetes mellitus (on-off hypoglycemic attacks), seizures, and was on insulin for three months, in addition to her menarche (irregular) having persistent hypophosphatemia on phosphate supplements." (PMID 40313484, 2025). "The case report shows the safety and efficacy of insulin treatment with Advanced Hybrid Closed Loop (AHCL) system in a young patient affected by permanent neonatal diabetes mellitus (PNDM) due to chromosome 8 deletion syndrome involving the GATA4 gene." (PMID 39457190, 2024). "Similarly, variants in KCNJ11, ABCC8 and INS accounted for 50% of neonatal diabetes mellitus (NDM) cases and were sequenced by Sanger first in some studies." (PMID 37794142, 2023). "Insulin and C-peptide concentrations below detection limit (insulin <2 μU/ml; C-peptide <0.1 ng/ml) led to the diagnosis of neonatal diabetes mellitus and initiation of intravenous insulin substitution." (PMID 33935973, 2021). "Insulin secretion in sulfonylurea-treated KCNJ11 permanent neonatal diabetes mellitus (PNDM) is thought to be mediated predominantly through amplifying non-KATP-channel pathways such as incretins." (PMID 31908791, 2019). "Mutations in the human insulin (INS) gene, e.g. INSC96Y, can cause permanent neonatal diabetes mellitus." (PMID 29419487, 2018). "At 8 days after birth, INSC94Y animals developed cataracts and at 4.5 months they showed signs of permanent neonatal diabetes mellitus, including reduced body weight, decreased β-cell mass and reduced fasting insulin levels." (PMID 29419487, 2018). "We previously reported that patients with permanent neonatal diabetes mellitus (PNDM) due to proteotoxic MIDY mutations have fasting hyperglucagonemia, suggesting loss of insulin- mediated intra-islet suppression of glucagon production." (PMID 28702245, 2016). "Mutations in KATP channel genes can result in hypo- or hypersecretion of insulin, as in neonatal diabetes mellitus and congenital hyperinsulinism, respectively." (PMID 27118464, 2016). "According to the difference in insulin dependency, NDM can be divided into transient neonatal diabetes mellitus (TNDM) and permanent neonatal diabetes mellitus (PNDM)." (PMID 36686471, 2022). "For example, among the 19 diseases with ‘Ketosis’ as clinical sign, two of them were classified as oligogenic: maple syrup urine disease with 3 genes (BCKDHA, BCKDHB and DBT) and Permanent neonatal diabetes mellitus with 4 genes (GCK, INS, KCNJ11 and ABCC8)." (PMID 28715999, 2017).
neonatal diabetes mellitus (continued). "Similarly, in a clinical case of transient neonatal diabetes mellitus where the infant was born with IUGR and umbilical plasma concentrations of insulin were undetectable, IGFI was lower than normal and IGFII was within the normal range." (PMID 34708692, 2021). "Accurate molecular diagnosis of monogenic non-autoimmune neonatal diabetes mellitus (NDM) is critical for patient care, as patients carrying a mutation in KCNJ11 or ABCC8 can be treated by oral sulfonylurea drugs instead of insulin therapy." (PMID 21049026, 2010). "However, loss of β-cell mass and identity still occurs in mouse models of human KATP-gain-of-function induced Neonatal Diabetes Mellitus (NDM), in the absence of insulin secretion." (PMID 35180212, 2022).
pancreatic insufficiency (46 papers, 2008 to 2026). "This procedure carries a high risk of total pancreatic insufficiency, requiring continuous replacement of insulin and pancreatic enzymes." (PMID 40282957, 2025). "Challenges remain in consistently achieving high islet yields and durable insulin independence, as well as managing exocrine pancreatic insufficiency post-surgery." (PMID 40747090, 2025). "Poor weight gain owing to pancreatic exocrine insufficiency improved with pancreatic enzyme replacement; the resulting improvement in nutrient absorption necessitated an increase in insulin dosage." (PMID 40476119, 2025). "Diagnostic clues include a history of pancreatic surgery or trauma, low insulin requirements, unpredictable glucose swings, and concomitant exocrine pancreatic insufficiency." (PMID 41146800, 2025). "Insulin secretion within 30 minutes of nutrient ingestion is reduced in people with cystic fibrosis (PwCF) and pancreatic insufficiency and declines with worsening glucose tolerance." (PMID 38444582, 2024). "According to the literature, the early diagnosis and therapy of exocrine pancreatic insufficiency and insulin therapy had a positive effect on the growth prognosis in patients with GATA6 gene variants and was confirmed in our clinical case." (PMID 39596087, 2024). "None of the patients progressed to chronic pancreatitis, long-term exocrine pancreatic insufficiency, or required long-term insulin therapy." (PMID 39439952, 2024). "The aim of this study was to investigate insulin secretion, insulin sensitivity, disposition index and insulin clearance by glucose tolerance status in individuals with cystic fibrosis and exocrine pancreatic insufficiency." (PMID 39093413, 2024). "There is a known correlation and plausible biological mechanism linking pancreatic insufficiency and β cell function, with pancreatic insufficient patients showing lower glucose tolerance and lower insulin secretion." (PMID 36983651, 2023). "Compared to healthy ASD controls, CF patients showed low cholesterol and insulin levels, in line with a CF pancreatic insufficiency phenotype." (PMID 34635725, 2021). "We present the case of a 33-year-old primigravida woman with CFRD (ΔF508 homozygote, with mild pulmonary involvement) on insulin therapy and treatment for exocrine pancreatic insufficiency, who developed subclinical hypothyroidism during gestation." (PMID 32742862, 2020). "Both study and control groups were similar with respect to sex, sweat chloride level, pancreatic insufficiency, and requirement for insulin and steroids." (PMID 18325250, 2008). "Furthermore, when the prevalence of EPI with different severities was explored, it was noticed that severe pancreatic exocrine insufficiency tends to occur in patients with higher insulin requirements." (PMID 36213198, 2022). "At the moment, insulin levels and the HOMA index have slightly decreased, but signs of exocrine pancreatic insufficiency have appeared in the form of a decrease in pancreatic elastase in the faeces — a consequence of further fatty tissue replacement, i.e., the development of pancreatic steatosis." (PMID 41198044, 2025). "This indicates that the blunted response of insulin in POMC-Cre ERt2:: FASNflox/flox mice is not due to pancreatic insufficiency, but rather to increased sympathetic tone." (PMID 40541585, 2025). "We evaluated the T1 values of the pancreas using a modified Look-Locker inversion recovery sequence (MOLLI), pancreatic exocrine insufficiency (PEI) by fecal elastase 1 (FE1) values, and pancreatic endocrine insufficiency using fasting insulin and blood glucose levels to calculate the HOMA-β." (PMID 32531933, 2020). "Here we accounted for differences in pancreatic insufficiency, and, perhaps more importantly, we included only post-puberal patients, as younger patients displayed a puberty-related increment in insulin secretion that we could not model reliably." (PMID 36983651, 2023).
Anorexia (45 papers, 2007 to 2026). Lack of desire to eat (loss of appetite). "We subjected the causal estimate of fasting insulin on the risk for anorexia to a suite of sensitivity analyses to assess the rigor of our derived IVW estimate and evidence of violations of core MR assumptions." (PMID 32920595, 2021). "As a result, we classified these trait pairs as having relatively weak evidence of causation in comparison to the fasting insulin to anorexia model." (PMID 32920595, 2021). "Despite these caveats and other methodological challenges associated with causal inference using IVs, we believe the fasting insulin—anorexia model to be reliable." (PMID 32920595, 2021). "The causal estimate between fasting insulin and anorexia using both the MR-PRESSO and GSMR approaches was also practically identical to the IVW estimator, although the GSMR estimate displayed a larger standard error (ORGSMR = 0.48, [95% CI:0.30–0.79], P = 3.7 × 10−3)." (PMID 32920595, 2021). "This may contradict the putative risk-decreasing effect of insulin on anorexia we observed in our study, however, there is evidence of a significant sexual dimorphism in this phenomenon." (PMID 32920595, 2021). "Given the genetic correlation between fasting insulin and anorexia, we used a latent causal variable model to determine the proportion of trait one (fasting insulin) that genetically causes trait two (anorexia), which was quantified as the mean posterior estimate of the GCP." (PMID 32920595, 2021). "This insulin-activated PI3K–Akt pathway may be linked to anorexia, as the administration of PI3K inhibitors has been shown to hinder the effect of insulin on lowering food intake." (PMID 27812350, 2016). "Furthermore, a well-powered, sex stratified GWAS of anorexia could be utilised to formally test whether the impact of insulin on anorexia risk displays sexual dimorphism, with sexual dimorphisms likely also evident in glycaemic traits themselves." (PMID 32920595, 2021). "Insulin requirements were tapered off; however, persistent anorexia and dyspnea led to the diagnosis of hypopituitarism through endocrine testing." (PMID 41536580, 2026). "Persistent inflammation accelerates PEW by promoting systemic protein catabolism, inducing anorexia, reducing voluntary activity and promoting insulin resistance." (PMID 38918730, 2024). "They suggested that insulin, together with neuropeptide Y (NPY), are causative factors of LPS-induced anorexia, as insulin concentrations increased from the second hour after LPS injection." (PMID 35897684, 2022). "The association between a natural log transformed pmol/L increase in fasting insulin and odds of anorexia yielded an odds ratio of 0.48 [95% CI: 0.33–0.71]." (PMID 32920595, 2021). "We revealed a significant protective effect of a unit increase [ln(pmol/L)] in fasting insulin levels on anorexia after the applying Bonferroni correction (OR = 0.48, [95% CI:0.33–0.71], P = 2.27 × 10−4)." (PMID 32920595, 2021). "Both NPY/AgRP and POMC are important downstream targets of insulin, and one of the core roles of insulin is to produce anorexia by suppressing the NPY/AgRP neurons and stimulating POMC neurons." (PMID 33868169, 2021). "As anorexia is significantly more prevalent in females it is possible that the sexual dimorphic effect of insulin on hunger signalling is contributing to this discrepancy in prevalence." (PMID 32920595, 2021). "Given the nature of the clinical presentation of anorexia, the effect of insulin on hunger and satiety is particularly pertinent." (PMID 32920595, 2021). "Hypothalamic inactivation of PDE3B by a specific inhibitor or a genetic deletion blunts central insulin-induced anorexia or weight gain, respectively." (PMID 30875909, 2019). "Insulin can affect appetite by acting on hypothalamic neurons, promoting anorexia by decreasing NPY and stimulating POMC expression and through regulating ghrelin suppression." (PMID 28677623, 2017).
Anorexia (continued). "This was the case with this patient, as psychosomatic care for anorexia initiated after the renal biopsy resulted in the gradual deterioration of the patient’s glycemic control, thus necessitating the administration of insulin." (PMID 22519964, 2012). "In contrast, sodium selenite treatment could be useful during catabolic process, such as anorexia, by inducing the insulin-signaling process since it clearly increases GLP-1 serum levels." (PMID 37237989, 2023). "However, during experimental endotoxemia, they observed a rapid increase in cortisol (stress marker) and insulin concentrations and thus suggested insulin as a mediator of observed fever and anorexia." (PMID 35897684, 2022). "Further investigation is required to explore the relationship between insulin levels and anorexia." (PMID 32920595, 2021). "Whilst the LCV GCP estimate was not significant, there was strong evidence that the causal direction was not anorexia to insulin [H0: GCP= −1, P = 3.6 × 10−104], in accordance with the Steiger directionality test results." (PMID 32920595, 2021). "The negative relationship between elevated insulin and anorexia risk derived in this study supports the negative genetic correlation observed between the two GWAS studies by LDSC." (PMID 32920595, 2021). "Consequently, it seems most beneficial for future interventions to target CCK, leptin, PYY and insulin when investigating methods to augment energy intake to reduce the anorexia of ageing from an endocrine perspective." (PMID 31432431, 2020). "A previous study showed that an intraperitoneal (ip) injection of Ga every other day for 1 week at a dose of 4 mg/kg BW decreased blood insulin levels with increased blood glucose levels, possibly due to its toxic induction of anorexia in HFD-induced obese mice." (PMID 32792584, 2020). "Chemotherapy-induced gastrointestinal disorders and anorexia could lead to starvation or low glucose levels, leading to decreased levels of insulin/IGF-1." (PMID 32709007, 2020). "Patients with HF are frequently malnourished due to gastrointestinal oedema,anorexia leading to reduced nutrient intake or inadequate absorption,inflammatory cytokine-induced hypercatabolic syndrome, abnormal liver functiondue to hepatic congestion, and insulin resistance." (PMID 41209128, 2025). "To evaluate the potential role of tunicamycin-induced anorexia, the altered plasma levels of insulin or free fatty acids in the redistribution of fatty acids from adipose tissue to liver, we performed pair-feeding studies and measured plasma insulin and free fatty acid concentrations." (PMID 35162995, 2022). "The role of insulin signalling and glucose metabolism in the brain, and its interplay with the periphery, is complex, necessitating further research to specifically understand how fasting insulin could exert a protective effect on anorexia." (PMID 32920595, 2021). "In addition, glycaemic abnormalities have been observed through direct serum measurement, including an association of elevated glycated haemoglobin with attention deficit hyperactive disorder (ADHD), insulin resistance with psychotic experiences, and elevated insulin sensitivity in anorexia." (PMID 32920595, 2021). "Insulin levels increase with age, and insulin may promote the development of anorexia." (PMID 33071750, 2020). "Moreover meal related insulin secretion is altered in human subjects with anorexia." (PMID 23382817, 2013). "However, unlike the fasting response, the insulin resistance is likely to be largely cytokine induced, plus, it is usually associated with pyrexia (increased futile cycling & thermogenesis) and anorexia – it is a hypermetabolic response." (PMID 17531095, 2007). "In fact, a synergic effect between IL-1 and CCK inducing anorexia has been described, while IL-1 and GIP are factors that stimulate insulin release by the pancreas." (PMID 31191339, 2019).